TYW5 (tRNA-yW synthesizing protein 5)
Description:
tRNA hydroxylase that acts as a component of the wybutosine biosynthesis pathway. Wybutosine is a hyper modified guanosine with a tricyclic base found at the 3'-position adjacent to the anticodon of eukaryotic phenylalanine tRNA. Catalyzes the hydroxylation of 7-(a-amino-a-carboxypropyl)wyosine (yW-72) into undermodified hydroxywybutosine (OHyW*). OHyW* being further transformed into hydroxywybutosine (OHyW) by LCMT2/TYW4. OHyW is a derivative of wybutosine found in higher eukaryotes.
Synonyms: hTYW5; C2orf60; FLJ37953
Tractability: Small molecule: a structure with a bound ligand is known; it has a high-quality binding pocket. PROTAC: ubiquitination databases record sites on it; its protein half-life has been measured.
Gene: Protein-coding gene on chromosome 2 (199,928,913 to 199,955,736, reverse strand). Ensembl gene ENSG00000162971.
Subcellular location (Human Protein Atlas): Mitochondria
Pathways (Reactome):
Metabolism of RNA: Synthesis of wybutosine at G37 of tRNA(Phe)
Gene Ontology:
Molecular function: iron ion binding; protein binding; protein homodimerization activity; tRNA binding; tRNA(Phe) (7-(3-amino-3-carboxypropyl)wyosine37-C2)-hydroxylase activity
Biological process: wybutosine biosynthetic process
Cellular component: cytoplasm
Genetic constraint (gnomAD): Loss-of-function variants: 34 observed, 38.86 expected, observed/expected ratio (o/e) 0.87, 90% interval 0.67 to 1.16. The upper end of that interval is the gene's LOEUF score, 1.16, which puts it in group 5 of 6, group 1 being the genes least tolerant of losing a copy. Missense variants: 339 observed, 363.67 expected, observed/expected ratio (o/e) 0.93, 90% interval 0.85 to 1.02. Synonymous variants: 111 observed, 129.05 expected, observed/expected ratio (o/e) 0.86, 90% interval 0.74 to 1.01.
Homologues: Orthologues: chimpanzee TYW5 (100% identical), dog TYW5 (94% identical), pig TYW5 (93% identical), macaque TYW5 (90% identical), guinea pig TYW5 (90% identical), mouse Tyw5 (89% identical), rat Tyw5 (88% identical), tropical clawed frog tyw5 (76% identical), zebrafish tyw5 (66% identical). Paralogues in human: HSPBAP1 (23% identical), HIF1AN (22% identical), JMJD7 (21% identical), KDM8 (20% identical).
Diseases named in the same sentence as TYW5 in open-access papers:
TYW5 is named in the same sentence as 10 diseases in open-access papers, as found by Europe PMC text mining. Sharing a sentence is not in itself a finding about the gene and the disease. The quoted sentences say what the papers report.
schizophrenia (2 papers, 2022). A major psychotic disorder characterized by abnormalities in the perception or expression of reality. "More importantly, little is known about how TYW5 genetic variations confer schizophrenia susceptibility or the role of TYW5 in schizophrenia pathophysiology." (PMID 35527273, 2022). "Our findings support that TYW5 is a schizophrenia risk gene whose expression may be regulated by schizophrenia GWAS SNPs." (PMID 35527273, 2022). "More studies are needed to determine whether TYW5 is a risk gene for schizophrenia." (PMID 35527273, 2022). "We also examined the expression level of TYW5 in the dorsolateral prefrontal cortex of schizophrenia cases and controls using expression data." (PMID 35527273, 2022). "Some researchers have shown a link between TYW5 and mental illnesses such schizophrenia, whereas others have been unable to corroborate this association." (PMID 35527273, 2022). "Furthermore, we explored the potential role of TYW5 in schizophrenia pathogenesis using induced pluripotent stem cells." (PMID 35527273, 2022). "In addition, TYW5 expression was also significantly higher in neurons induced from pluripotent stem cells of schizophrenia cases compared with controls." (PMID 35527273, 2022). "Finally, TYW5 expression modulation in related (eventually patient) cell lines or animal models will provide further evidence for the potential role of TYW5 in schizophrenia." (PMID 35527273, 2022). "We found that TYW5 was significantly upregulated in DLPFC in patients with schizophrenia, which also suggests that TYW5 may act as a potential therapeutic target of SCZ." (PMID 35527273, 2022).
autism spectrum disorder (1 paper, 2022). A spectrum of developmental disorders that includes autism, and Asperger syndrome. "In addition, TYW5 may also be involved in the genetic susceptibility of mental illness that shares the common risk factor with SCZ, such as neurodevelopment-related disorders autism spectrum disorder and bipolar disorder." (PMID 35527273, 2022).
Sleep apnea (1 paper, 2017). An intermittent cessation of airflow at the mouth and nose during sleep is known as sleep apnea. "Suggestive associations of symptoms of sleep apnea were observed with 11 rare variants (located in KANK2, LCN6, TRAF3, PLEK, HIF1A, SLC45A3, ERCC1/CD3EAP, MRGPRE, GRAMD4, TYW5, CST5)." (PMID 29093733, 2017).
testicular germ cell tumor (1 paper, 2022). A germ cell tumor arising from the testis. "Recent studies have also shown expression dysregulation of TYW5 in cancer, including testicular germ cell tumors." (PMID 35527273, 2022).
neurodevelopmental disorder (1 paper, 2022). A behavioral and cognitive disorder with onset during the developmental period that involves impaired or aberrant development of intellectual, motor, or social functions. "TYW5 is an essential tRNA hydroxylase, and previous studies have found that tRNA alteration defects are linked to many neurodevelopmental disorders." (PMID 35527273, 2022).
tumor (1 paper, 2022). "Also, studies have shown that TYW5 regulates migration, invasion, and tumor cell proliferation." (PMID 35527273, 2022).
TYW5 also shares sentences with these, for which no sentence is quoted: cancer (2 papers); mental illness (2); bipolar disorder (1); brain disorder (1).